WWOX (WW domain containing oxidoreductase)
Diseases named in the same sentence as WWOX in open-access papers (continued):
Sharing a sentence is not in itself a finding about the gene and the disease.
breast cancer (continued). "In contrast to our previous observations in breast cancer in which we observed a strong correlation between ER and PR with WWOX expression, in this ovarian study, only PR was associated with WWOX expression." (PMID 15982416, 2005). "We observed that ectopic WWOX expression inhibited anchorage independent growth and in vivo tumorigenicity of highly aggressive breast carcinoma lines, suggesting a putative tumor suppressor role for this novel protein." (PMID 15982416, 2005). "This antibody has been used to detect WWOX protein expression in several breast cancer cell lines, demonstrating that altered WWOX gene expression correlated with altered WWOX protein levels." (PMID 15266310, 2004). "Furthermore, in human breast cancer samples, WWOX expression was inversely correlated with the level of the glucose transporter GLUT1, a direct target of HIF1α." (PMID 41007296, 2025). "For luminal breast cancers, we found that high WWOX/HIF1A ratios demonstrate a more robust anti-tumour immune response, as evidenced by increased expression of CD8A and FOXP3, which are instrumental in recruiting cytotoxic T-cells and suppressing pro-tumourigenic inflammation." (PMID 41007296, 2025). "WWOX tumour suppressor function was studied in several breast cancer cell lines." (PMID 41007296, 2025). "This suggests that WWOX expression levels may serve as a predictive marker for the malignant progression of breast cancer." (PMID 41228229, 2025). "In basal-like and HER2-positive breast cancers, we demonstrated that a low WWOX/HIF1A ratio is particularly detrimental, as it triggers HIF1α-mediated upregulation of immunosuppressive mediators such as TLR4, NOTCH1, PTX3, and IL6R, alongside glycolytic enzymes like GLUT1 and HK2." (PMID 41007296, 2025). "However, to date, there is a paucity of data available examining the effect of WWOX/HIF1α signalling pathway on patient survival in breast cancer, hepatocellular, and glioblastoma." (PMID 41007296, 2025). "We observed a similar dichotomy in HER2-positive breast cancers, where a favourable WWOX/HIF1A ratio facilitates robust DNA repair and counteracts hypoxia-induced signalling, which would otherwise promote angiogenesis and glycolytic reprogramming linked to poor prognosis." (PMID 41007296, 2025). "Additionally, WWOX regulates the migration of breast cancer and melanoma cells in vitro and inhibits metastasis in vivo by targeting p-STAT3." (PMID 41228229, 2025). "Given the effect of combined deletion of Wwox and Brca1 on mammary tumor formation and the known effect of WWOX/BRCA1 interaction on DNA repair pathway choice in vitro, we next set to examine which DSB repair pathway is favored in tumors of K14-Cre;Brca1fl/fl;Wwoxfl/fl mice." (PMID 38499540, 2024). "The reduction or absence of WWOX expression has been associated with several cancers, including breast cancer, thyroid cancer, oral cancer and lung cancer." (PMID 37974179, 2023). "The WWOX tumor suppressor gene coding region is located on chromosome 16q23.3–24, which is recognized as the one of the most common fragile sites of genetic change in breast cancer." (PMID 35290621, 2022). "Furthermore, in a rescue experiment in MCF7 breast cancer cells, the upregulation of WWOX suppressed HIF1α target gene expression." (PMID 36271927, 2022). "Moreover, it shows one of the highest WWOX gene expressions among all studied breast cancer cell lines." (PMID 35290621, 2022). "Another protein ANXA1 (downregulated in MC7 and BT20 E2 treated and WWOX-depleted cells) which was previously reported to regulate EMT and is associated with highly invasive basal-like breast cancer phenotype was found also to contribute to trastuzumab resistance through AKT activation." (PMID 35290621, 2022).
breast cancer (continued). "Additionally, ER-positive MCF7 breast cancer cells showed increased aggressiveness when estradiol action was combined with lowered WWOX protein levels." (PMID 35290621, 2022). "Evidence suggests the inhibitory role of WWOX tumor suppressor gene in breast cancer." (PMID 35186006, 2021). "The WWOX protein is capable of suppressing the transcriptional activity of oncogenic AP-2γ by sequestering it in the cytoplasm; for example, in the case of breast carcinoma, WWOX inactivation can induce tumor progression by stimulating AP-2γ nuclear translocation." (PMID 33718178, 2021). "Additionally, nuclear β-catenin levels were reduced when WWOX was ectopically expressed in MDA-MB231 metastatic breast cancer cells." (PMID 32300104, 2020). "When mice received Zfra4-10 or WWOX7-21 peptide alone followed by 4T1 breast cancer inoculation, these mice developed endogenous complex formation of WWOX with many target proteins, including ERK, C1qBP, NF-κB, Iba1, p21, CD133, JNK1, COX2, Oct4, and GFAP in the spleen, brain, and lung." (PMID 32764489, 2020). "Moreover, loss of WWOX expression in MCF7 breast cancer cells was found to be associated with the increased DSB level following DNA damage, highlighting the role of WWOX in genomic stability." (PMID 30211123, 2018). "In addition, breast cancer tissue microarrays have shown that in breast cancer samples, WWOX expression is inversely correlated with levels of the glucose transporter GLUT1, which is known to be a direct target of HIF1α." (PMID 30211123, 2018). "In breast cancer, WWOX gene is lost even in pre-invasive stages." (PMID 30619734, 2018). "Finally, they demonstrated that WWOX expression inversely correlates with HIF1α target gene Glucose transporter 1 gene (Glut1) in breast cancer tissue samples." (PMID 30619734, 2018). "Our data suggested that the involvement of the WWOX pathway in breast cancers might have been underestimated." (PMID 30285739, 2018). "Inactivation of WW domain-containing oxidoreductase (WWOX), the gene product of the common fragile site FRA16D, is a common event in breast cancer and is associated with worse prognosis of triple-negative breast cancer (TNBC) and basal-like breast cancer (BLBC)." (PMID 30082886, 2018). "In breast cancer cells, the authors showed that WWOX knock down increases HIF1α in MCF7 cells." (PMID 30619734, 2018). "Moreover, recent studies have shown a correlation between WWOX expression and the clinical outcome of breast cancer." (PMID 30619734, 2018). "WWOX was also found to play a role in breast cancer metastasis." (PMID 30619734, 2018). "Importantly, restoration of WWOX expression inhibits breast cancer cell growth both in vitro and in vivo, further proposing a tumor suppressive function." (PMID 30082886, 2018). "WWOX was also proved to be a potent prognostic marker in breast cancer." (PMID 30211123, 2018). "In addition, WWOX was shown to play an important role in hepatocyte growth factor (HGF) mediated mesenchymal to epithelial transition (MET) in breast cancer bone metastasis." (PMID 30619734, 2018). "However, low or decreased expression and aberrant transcription of WWOX has been reported in several types of cancer, including nonsmall cell lung cancer (85%), prostate cancer (84%), breast cancer (63%), and oral cancer (40%)." (PMID 28426730, 2017). "WWOX gene has been identified in many cancer cells, for example upregulation was found during prostatic and breast cancer progression from hyperplasia to metastasis Targeted deletion of Wwox in mice has been found to cause growth retardation and early postnatal death." (PMID 27495153, 2016).
breast cancer (continued). "As in the MDA-MB 231 breast cancer cell line, increased expression of WWOX resulted in increased invasion through basal membrane, which may be connected with WWOX regulation of cell motility, and may perhaps exert an influence on tissue remodelling." (PMID 24938873, 2014). "WWOX (WW domain-containing oxidoreductase) was originally cloned by our laboratory because it was observed to reside in a chromosomal region (ch16q23) commonly affected by deletions in breast cancer." (PMID 24330518, 2013). "Ectopic expression of WWOX in breast cancer cells inhibited tumor growth in vivo, indicating that WWOX might be a candidate tumor-suppressor." (PMID 22084676, 2010). "Since WWOX function is usually lost in breast cancer, it will be interesting to test whether a small molecule that resembles WWOX WW domain would inhibit the function of HIF1α and shifts cancer cell metabolism from a glycolysis dependent to a normal metabolism." (PMID 30619734, 2018). "Therefore, there has been tremendous efforts to uncover whether WWOX somatic deletion leads to mammary tumor formation." (PMID 30370248, 2018). "Furthermore, WWOX was shown to interact with p73β in MCF7 breast cancer cell line." (PMID 30619734, 2018). "Additionally, evidence from in vivo overexpression studies suggests that WWOX might suppress the carcinogenetic effect of MDA-MB-435 breast cancer cells." (PMID 28426730, 2017). "WWOX is generally strongly expressed in various normal tissues, but its expression by immunohistochemistry (IHC) is absent or weak in many cancers arising from tissues that generally express WWOX, including cancers of the breast, ovary, bladder, and esophagus, and in leukemias." (PMID 25024751, 2014). "Given the relevance of ANGPTL4 as a key determinant of lung metastatic phenotypes for breast cancer cells and our observations of a clear inverse behavior between WWOX and ANGPTL4 at the transcript and protein level, we investigated whether this inverse relationship extended to breast cancers." (PMID 24330518, 2013). "Importantly, it has been determined that over 70% of estrogen receptor alpha (ER) negative breast cancers express little or no WWOX protein, suggesting an inverse association between WWOX expression and increasing breast cancer aggressiveness." (PMID 24330518, 2013). "In osteosarcoma, WWOX binds to RUNX2 via the WW1 domain, thereby inhibiting its transactivation ability, whereas in breast cancer, the same domain facilitates the cytoplasmic sequestration of SMAD3, which suppresses its transcriptional activity." (PMID 41228229, 2025). "These molecular alterations are evident in breast cancer subtypes (basal, HER2-positive, luminal A and B), HCC, GBM, and LGG, underscoring the universal relevance of the WWOX/HIF1A axis in tumour biology." (PMID 41007296, 2025). "In this study, we investigated the interplay between WWOX and BRCA1, both frequently inactivated in TNBC, on mammary tumor development and on DNA double-strand break (DSB) repair choice." (PMID 38499540, 2024). "In human breast cancer, there is evidence of a correlation between nuclear BRCA1 and WWOX expression." (PMID 38499540, 2024). "This study developed a signature featuring 8 OARGs (HLA-B, RBBP8, SPRY4, WT1, WWOX, UPRT, PELO, ZNF208) and determined its prognostic and functional implications in breast cancer patients." (PMID 36960071, 2023). "It has been shown that WWOX physically binds to SMAD3 through its WW1 domain, leading to inhibition of its activity and enhanced TGF-β signaling in breast cancer cells." (PMID 36572673, 2022). "The WWOX gene is located at 16q23.1–23.2, in a region containing the common fragile sites FRA16D, and its deletions have been observed in a large number of breast cancer cases." (PMID 33808143, 2021). "Since VOPP1 and WWOX have concomitant patterns of expression, we evaluated the presence of significant interaction between VOPP1 and WWOX expression on breast cancer metastasis-free survival rates." (PMID 30285739, 2018).
breast cancer (continued). "It was proposed that the elevation in WWOX expression is responsible for altering the HGF/Met/E.cadherin signaling axis and thus reducing breast cancer metastasis to the bone." (PMID 30619734, 2018). "WW domain-containing oxidoreductase (WWOX) is a tumor suppressor gene, and reduced expression of WWOX is noted in multiple cancers such as HCC, non-small cell lung cancer, osteosarcoma, breast cancer, and prostate cancer." (PMID 28708106, 2017). "In summary, we hypothesize that the progressive loss of WWOX expression in advanced breast cancer contributes to deregulating the TGFβ pathway and, more importantly, may explain some of the pro-metastatic effects resulting from TGFβ/SMAD3 hyperactive signaling in advanced breast cancer." (PMID 24330518, 2013). "Since loss of WWOX expression increases with breast cancer progression and it behaves as an inhibitor of SMAD3 transcriptional activity these observations may help explain, at least in part, the paradoxical pro-tumorigenic effects of TGFβ signaling in advanced breast cancer." (PMID 24330518, 2013). "Surprisingly, although FRA16D is a LOH site in breast, lung, esophageal, gastric, pancreatic carcinomas and lymphomas, WWOX mRNA is overexpressed in multiple breast cancer cell lines, including MCF-7, MDA-MB-453, SKBR3 and ZR-75-1." (PMID 23109895, 2012). "This genomic safeguarding is particularly evident in basal-like breast cancer, where we demonstrated that elevated WWOX expression not only supports detoxification and nucleotide metabolism but also reinforces DNA repair pathways." (PMID 41007296, 2025). "In addition, The LPxY motif‐containing tumor suppressor WW domain‐containing oxidoreductase (WWOX) is also an ITCH substrate; depletion of WWOX induces anchorage‐independent proliferation of MCF‐7 cells, and knockout mice of this gene develop mammary tumors." (PMID 34927784, 2022). "Expression of WWOX and phosphorylated STAT3 are negatively correlated in breast cancer cells." (PMID 33946771, 2021). "In contrast, the MCF7 breast cancer cell line does not show evidence of CpG methylation in the WWOX gene promoter and aberrant splicing events result in atypical nuclear localization and attenuated WWOX function." (PMID 33129329, 2020). "In addition, recent studies revealed that WWOX levels are induced upon DNA damage and that WWOX interacts with DNA damage checkpoint proteins ATM31 and BRCA135 to regulate DNA repair in breast cancer cells." (PMID 30082886, 2018). "Surprisingly, none of these models developed mammary tumors hence questioning initiation role of tumor suppressor WWOX." (PMID 30370248, 2018). "Furthermore, the expression of WWOX and ERBB4 was significantly lower in tissues derived from lymph node matched metastases than primary breast cancer tissues." (PMID 30211123, 2018). "Our study aimed at better characterizing the role of WWOX and VOPP1 binding in breast cancer." (PMID 30285739, 2018). "They observed that 27% of estrogen-positive breast carcinomas were negative for WWOX expression, compared with 46% for ER– cancers (p = 0.0054)." (PMID 30211123, 2018). "WWOX suppresses TGFβ/SMAD signaling, and WWOX mouse mutants promote mammary tumor growth." (PMID 29069730, 2017). "In addition, studies show that phosphorylated WWOX is able to physically bind to the PPxY motif of WBP2 and inhibit the ER transactivation pathway, further attenuating the process of breast cancer." (PMID 28724435, 2017).
breast cancer (continued). "In the absence of WWOX, a condition that emulates advanced breast cancer, SMAD3 can enter the nucleus uninhibited." (PMID 24330518, 2013). "The mammary tumors developed in these mice were indeed negative for WWOX expression." (PMID 38499540, 2024). "Additionally, in breast cancer samples, WWOX expression negatively correlated with GLUT1 levels, which supports the hypothesis that WWOX modulates cancer glucose metabolism." (PMID 36271927, 2022). "Such aberrant transcripts encoding truncated proteins (predominantly devoid of oxidoreductase-coding sequence) were found not only in the breast cancer cell lines and tumor samples, but also in various cancerous tissues; however, no other form of WWOX truncated protein was found." (PMID 30211123, 2018). "Importantly, mammary tumors in Wwox-heterozygous C3H mice were mostly ER-negative and PR-negative, expressing CK-14, hence reminiscent of the common WWOX inactivation in TNBC and in particular BLBC25." (PMID 30082886, 2018). "These recent observations defining WWOX as a direct player in the DDR30,31,35 led us to pursue our hypothesis and test whether specific targeted deletion of Wwox in murine mammary epithelium results in mammary tumor formation." (PMID 30082886, 2018). "WWOX is a tumor suppressor gene that shows reduced or no expression in certain cancer models, while over-expression induces dramatic inhibition of tumorigenicity in breast cancer." (PMID 21072196, 2010). "The impact of the WWOX/HIF1A ratio on EMT, invasiveness, and angiogenesis is not confined to breast cancer but extends to brain tumours and HCC as well." (PMID 41007296, 2025). "We generated and characterized a transgenic mouse model (K14-Cre;Brca1fl/fl;Wwoxfl/fl) and observed that mice lacking both WWOX and BRCA1 developed basal-like mammary tumors and exhibited a decrease in 53BP1 foci and an increase in RAD51 foci, suggesting impaired DSB repair." (PMID 38499540, 2024). "In addition, we observed copy losses of the negative regulators SUFU, as well as of the tumor suppressor WWOX, a newly identified negative modulator of GLI1 in breast cancer." (PMID 27095580, 2016).